FOXM1 (forkhead box M1)
Diseases named in the same sentence as FOXM1 in open-access papers (continued):
Sharing a sentence is not in itself a finding about the gene and the disease.
breast cancer (continued). "To determine the roles of FoxM1 in the tumorigenesis of breast cancer cells by activating the PDGF/AKT pathway, we injected 4T07-FoxM1 cells into the mammary fat pads of nude mice." (PMID 25869208, 2015). "We showed that FoxM1 enhances the survival and growth of human breast cancer cells through the PDGF/AKT signaling pathway." (PMID 25869208, 2015). "High expression of B-MYB is linked to breast cancer, and increased expression of FOXM1 correlates with a poor prognosis in breast cancers." (PMID 25909288, 2015). "Studies have shown that FoxM1 stimulates the transcription of estrogen receptor-alpha and is significantly correlated with estrogen receptor-alpha in breast cancer cells." (PMID 25869208, 2015). "Aberrant activation or expression of FoxM1 also promotes the development of acquired drug resistance in various tumors, including breast cancer." (PMID 25869208, 2015). "Our study demonstrated that FoxM1 activates the PDGF/AKT signaling pathway by stimulating the transcription of PDGF-A in breast cancer cells." (PMID 25869208, 2015). "We also analyzed microarray dataset derived from BT-20 breast cancer cells transfected with mock or FoxM1 siRNA (GSE2222)." (PMID 26264222, 2015). "We examined the expression levels of FoxM1 in two mouse mammary carcinoma cell lines (4T07 and 4T1), in two human mammary carcinoma cell lines (BT474 and MDA-MB-231), and in an immortalized normal human breast epithelial cell line (MCF 10A)." (PMID 25869208, 2015). "Our examination of several large data sets cumulatively representing about 1,000 ER+ breast tumors indicates that high FOXM1 expression occurs in about 20% of ER+ breast cancers." (PMID 25213081, 2014). "The level of FOXM1 expression has also been shown to be correlated with the effectiveness of a number of other breast cancer therapies including herceptin, gefitinib, lapatinib, paclitaxel, and cis-platinum." (PMID 24636070, 2014). "The cluster patterns indicate that FOXM1 has specific (C1 and C4) and common binding sites with ERα (C2 and C3) and highlight the ERα-dependent and -independent roles of FOXM1 in the breast cancer phenotype." (PMID 25213081, 2014). "FOXM1 regulates XRCC1 and BRCA2 in HER positive breast cancer, in triple-negative breast cancer, however, FOXM1 transactivates EXO1 and PLK4 in response to doxorubicin." (PMID 24824601, 2014). "Collectively, these findings suggest that FOXM1 is a cellular target of casticin in breast cancer cells." (PMID 24765206, 2014). "They highlight the relevance of FOXM1 as a therapeutic target to be considered for reducing invasiveness and enhancing breast cancer response to endocrine treatments." (PMID 25213081, 2014). "In summary, our study suggests that FOXO3a/FOXM1/survivin are cellular targets and markers of casticin action in breast cancer." (PMID 24765206, 2014). "For example, a novel thiazole antibiotic, thiostrepton, selectively induced cell cycle arrest and cell death in breast cancer cells through the downregulation of FOXM1 expression." (PMID 24765206, 2014). "Several lines of evidence demonstrate that overexpression of FoxM1 occurs in a wide variety of human tumors frequently, including medulloblastoma, colorectal cancer, hepatocellular carcinoma, breast cancer, non-small cell lung cancer and so on." (PMID 25522167, 2014). "As casticin targets FOXM1 through FOXO3a in breast cancer, it is possible to increase the efficacy of casticin by targeting FOXM1." (PMID 24765206, 2014). "In the present study, the role and regulation of FOXM1 in response to casticin treatment in breast cancer cells was investigated." (PMID 24765206, 2014). "Recent comprehensive profiling of breast cancer suggests a role for FoxM1 activation in the transcriptional maintenance of BBC." (PMID 24844244, 2014). "Use of a selective FOXM1 inhibitor proved very effective in restoring endocrine therapy sensitivity and decreasing breast cancer aggressiveness." (PMID 25213081, 2014).
breast cancer (continued). "Approximately 70% of breast cancers are estrogen receptor (ERα)-positive and there is increasing evidence to suggest that ERα and FOXM1 act as co-regulators." (PMID 23347430, 2013). "This confirms the therapeutic potential of targeting FOXM1, as thiostrepton treatment reduces the expression of genes whose high expression correlates with poor patient outcome in breast cancer." (PMID 23347430, 2013). "These authors showed that high levels of OGT are responsible for the increased activity of FOXM1 in breast cancer MCF-10A cells overexpressing the activated form of ErbB2." (PMID 23964270, 2013). "Meta-analysis of gene expression data from breast cancer patient studies identified FOXM1 as one of 117 genes comprising a gene expression signature predictive of survival." (PMID 23347430, 2013). "In breast cancer cell lines with acquired resistance for cisplatin or epirubicin FoxM1 was found to be overexpressed and its depletion was able to re-sensitize these cell lines to the respective genotoxic drug." (PMID 23467617, 2013). "Amplifications of FoxM1 gene has been reported in numerous tumors such as pancreatic carcinomas, breast cancer and hepatocellular carcinoma." (PMID 24204899, 2013). "Silencing of FoxM1 also led to higher sensitivity to doxorubicin in breast cancer cells in a xenograft mouse model." (PMID 23467617, 2013). "The data from our study suggest another mode of interaction of FOXM1, in this case co-binding with ERα in ERα-positive breast cancer cells." (PMID 23347430, 2013). "The differences in FOXM1 binding with ERα status in breast cancer cells contribute another dimension to the already complex mechanisms known to regulate FOXM1 transactivation." (PMID 23347430, 2013). "FOXM1 expression in breast cancer was found to correlate with levels of YWHAZ, a member of the 14-3-3 family of proteins and also with HER2 status." (PMID 23347430, 2013). "Consistently, several ROS inducers effectively killed breast cancer cells when combined with proteasome inhibitors or siRNA-mediated knockdown of FOXM1." (PMID 24342878, 2013). "Specifically, FOXM1 regulates a gene signature that correlates with poor prognosis in breast cancer patients, supporting the therapeutic potential in targeting FOXM1 in ER-positive breast cancer." (PMID 23347430, 2013). "For example, it has been reported that FOXO3a represses estrogen receptors α (ERα) activity in breast cancer cells through an alternative mechanism by which FOXO3a interacts and downregulates the expression of FOXM1." (PMID 23819460, 2013). "We have demonstrated that FOXM1 shows distinct patterns of binding depending on ERα status in breast cancer cells, but within an ER-positive context FOXM1 plays an important role in ERα signaling pathways." (PMID 23347430, 2013). "To date, some studies have revealed that FoxM1 expression can be driven primarily by the Hedgehog signaling pathway in gastric cancer, colorectal cancer, meningioma and breast cancer." (PMID 23110199, 2012). "Our observations now add regulation of FOXM1 as another important aspect of 14-3-3ζ activity in breast cancer and endocrine resistance." (PMID 21707964, 2011). "The thiazole antibiotic thiostrepton can specifically inhibit the expression of FOXM1 at gene promoter level in breast cancer cell lines, and therefore it was used to deplete the expression of FOXM1 in ovarian cancer cells." (PMID 21858223, 2011). "al. showed that thiostrepton represses FoxM1 expression and induces apoptosis in breast cancer cells." (PMID 19440351, 2009). "A recent study involving 3 independent breast cancer microarray datasets containing a total of 699 patients revealed that CEP55 and FOXM1 are amongst the signature prognostic markers which predicts breast cancer outcome." (PMID 19287496, 2009). "The role of FoxM1 in promoting cancer was further emphasized by the poor prognosis for breast cancer patients with higher levels of FoxM1 gene expression." (PMID 19672316, 2009).
breast cancer (continued). "Our analysis of the four breast cancer datasets yielded one obvious example of a relevant gene (FOXM1) with a high cwCLEAN score and the CLEAN score of zero in all four breast cancer datasets." (PMID 19640299, 2009). "FoxM1 is overexpressed in hepatocellular carcinomas, pancreatic carcinomas, breast cancers, non-small cell lung carcinomas, anaplastic astrocytomas and glioblastomas, basal cell carcinomas and intrahepatic cholangiocarcinomas." (PMID 19440351, 2009). "This is the first study showing a significant association between nuclear FOXM1 expression and abundant expression of HER2 in breast cancer (P = 0.045)." (PMID 18254960, 2008). "By use of a large tissue microarray (n = 250) we investigated the protein expression of FOXM1 in breast cancer specimens and normal breast tissues." (PMID 18254960, 2008). "We found that nuclear FOXM1 expression in breast cancer (IRS ≥ 2) shows a tendency towards unfavourable prognosis regarding overall survival as shown by Kaplan-Meier analysis (P = 0.110)." (PMID 18254960, 2008). "Next we analysed FOXM1 mRNA expression by realtime PCR in primary human breast cancers (n = 25) and normal mammary samples (n = 12) derived from formalin-fixed, paraffin-embedded tissues." (PMID 18254960, 2008). "On a large cohort of breast cancer specimens we performed a first systematic expression analysis of FOXM1 on both mRNA and protein level and subsequently studied FOXM1 expression with respect to clinicopathological parameters and patients' survival data." (PMID 18254960, 2008). "FOXM1 was found to be overexpressed in breast cancer in comparison to normal breast tissue both on the RNA and protein level (e.g. 8.7 fold as measured by realtime PCR)." (PMID 18254960, 2008). "The metastatic breast cancer cell line MDA-MB231 presented an exceptionally high level of FOXM1 expression." (PMID 18254960, 2008). "In line with the expression data in breast cell lines, FOXM1 mRNA was strongly upregulated in primary breast cancer specimens compared to normal mammary epithelial tissue." (PMID 18254960, 2008). "87% of breast carcinomas were shown to exhibit nuclear FOXM1 staining, compared to a percentage of 41% of normal breast tissue specimens showing nuclear FOXM1 expression." (PMID 18254960, 2008). "Recently, FOXM1 expression has been analysed in human breast carcinomas, showing that mRNA transcript levels of the FOXM1 gene were upregulated in tumour tissue as compared to normal breast tissue." (PMID 18254960, 2008). "Considering the whole tissue microarray 87% (187/204) of the breast carcinomas expressed nuclear FOXM1 versus 42% (19/46) of normal breast tissue specimens." (PMID 18254960, 2008). "Similarly, hyperactivated ARID1A, phospho-HDAC6 and FOXM1 in Ewing’s sarcoma and breast cancer remodel chromatin structure via phase separation, driving oncogenic transcription and tumor progression." (PMID 40507965, 2025). "Notably, FOXM1 also serves as a key mediator of estrogen-induced mitogenic signaling in breast cancer cells." (PMID 40720499, 2025). "In addition, we found that RGC-32 expression was positively correlated with the expression of FoxM1 in breast cancer patients." (PMID 40720499, 2025). "FOXM1 is linked to the expression of GLUT1 in hepatocellular carcinoma and breast cancer." (PMID 40713647, 2025). "FOXM1 is massively upregulated, with adjusted p-values below the limit of precision of the R software, so p < 2.2 × 10−308 in breast cancer (Log2 Fold Change = +4.36), lung squamous cancer (Log2 FC = +4.12), and the two uterine cancers (UCEC and UCS, with Log2 FC of +5.64 and +5.83)." (PMID 39858603, 2025). "This targeted approach based on both KPNA2 and FOXM1 expression patterns could lead to more personalized treatment strategies in HR+HER2- breast cancer." (PMID 40002266, 2025). "Therefore, the overexpression of YTHDF1 in breast cancer cells largely augments the expression of FOXM1 and promotes breast cancer cell proliferation, invasion, and EMT." (PMID 40003882, 2025).
breast cancer (continued). "Foxm1, an oncogenic transcription factor crucial for cancer initiation, progression, and drug resistance, is significantly upregulated in various cancers, including breast cancer." (PMID 40182023, 2025). "FOXO3A suppresses breast cancer stem cell properties and tumorigenicity via inhibition of FOXM1/SOX2 signaling, suggesting that FRMD8 may have an effect on breast cancer stem cells." (PMID 40213945, 2025). "We found that RGC-32 regulated FoxM1 expression in breast cancer cells in the presence of ERα." (PMID 40720499, 2025). "For instance, in breast cancer, FOXM1 undergoes LLPS to bind Forkhead consensus DNA elements." (PMID 41323740, 2025). "FOXM1 is a key mediator of mitogenic functions of ERα and estrogen in breast cancer cells." (PMID 40720499, 2025). "FOXM1 was identified as the most likely transcriptional factor of UBE2C in breast cancer cells." (PMID 40729680, 2025). "The expression of UBE2C was transcriptionally regulated by FOXM1 in breast cancer cells." (PMID 40729680, 2025). "Conversely, knockdown of FOXM1 downregulated the expression of UBE2C in breast cancer cells." (PMID 40729680, 2025). "However, the follow-up duration in our series is short, limiting our ability to demonstrate that HR+/HER2- breast cancer patients with high KPNA2 but low FOXM1 mRNA levels exhibit significantly better survival outcomes beyond the TCGA cohorts." (PMID 40002266, 2025). "In ER+ breast cancer cells, FOXM1 engages in core circadian gene cryptochrome 2 (CRY2) promoter hypermethylation by forming the FOXM1/DNMT3b (DNA methyltransferase 3b) complex; the FOXM1/DNMT3b complex binds to the CRY2 promoter directly to downregulate the expression of CRY2." (PMID 40003882, 2025). "Moreover, aberrant UBE2C expression was found to be transcriptionally regulated by forkhead box protein M1 (FOXM1) in breast cancer." (PMID 40729680, 2025). "In this context, the regulatory loop between FOXM1-miR-4741-CLDN4 overexpression may cooperatively promote breast cancer aggressiveness and chemoresistance." (PMID 40862714, 2025). "FOXM1 overexpression usually occurs in breast cancer and is always correlated with poor prognosis." (PMID 40003882, 2025). "This novel finding suggests that FOXM1 expression could serve as a valuable prognostic marker specifically in KPNA2-high HR+HER2- breast cancer patients." (PMID 40002266, 2025). "17d induced FOXM1 degradation and disrupted the FOXM1 pathway in breast cancer cells." (PMID 38791105, 2024). "FOXM1 is abnormally overexpressed and amplified in the majority of human cancers (such as ovarian cancer, colorectal cancer, esophageal cancer, breast cancer, prostate cancer, gastric cancer, and pancreatic cancer) and well demonstrated as a master transcriptional regulator in cancer development." (PMID 38697979, 2024). "Beclin-1 and LC3 are overexpressed in breast cancers and are associated with poor survival in TNBC patients, suggesting that targeting FOXM1 may suppress the tumor-promoting autophagic process." (PMID 39594778, 2024). "In anthracycline-resistant breast cancer cells, FOXM1 is highly upregulated." (PMID 38398147, 2024). "Notably, upregulation of FOXM1 has been reported to activate the Wnt/β-catenin signaling pathway, thus promoting the development of breast cancer." (PMID 38978058, 2024). "To characterize changes in breast cancer cells accompanying development of resistance to inhibitors of the oncogenic transcription factor, FOXM1, we investigated the suppression of cell death pathways, especially ferroptosis, in FOXM1 inhibitor-resistant cells." (PMID 38980505, 2024). "We also found that AURKB, BIRC5, CDCA8, and FOXM1 are all part of the meta-PCNA proliferation gene signature, and high levels of expression of genes in this signature are associated with poor prognosis in breast cancer." (PMID 39335162, 2024).
breast cancer (continued). "Our data suggest that rabeprazole and pantoprazole can inhibit FOXM1 and provide a targeted therapeutic option for breast cancer patients and other cancers with aberrant FOXM1 expression, laying the foundation for developing FOXM1-targeted personalized treatment approaches in future." (PMID 38918225, 2024). "So, both CA9 and FOXM1 were novel markers of poor prognosis for breast cancer patients." (PMID 38561760, 2024). "In addition, it has been described that FOXM1 promotes chemoresistance in breast cancer while its inhibition restores trastuzumab response." (PMID 38886738, 2024). "Thus, this study aimed to identify potential FOXM1 inhibitors through computational screening of drug databases, followed by in vitro validation of their inhibitory activity against breast cancer cells." (PMID 38918225, 2024). "Moreover, miR-802 inhibits FoxM1 decreasing the proliferation of breast cancer cells and miR-194 inhibits proliferation and migration of breast cancer cells, supporting the tumor-suppressive roles of these miRNAs." (PMID 39175471, 2024). "FOXP1, FOXA1, and FOXM1 may be used as potential biomarkers to predict the prognosis of patients with breast cancer." (PMID 38608123, 2024). "Additionally, FOXM1 is expressed in all stages of breast cancer and all breast cancer subtypes, including TNBC, ER+, and HER2+." (PMID 39594778, 2024). "In addition, the activated MAPK in tamoxifen-resistant breast cancer cells phosphorylates FOXM1 and induces its nuclear translocation and transcriptional activity." (PMID 38398147, 2024). "Moreover, FOXM1 knockdown reversed the inhibitory effects of CDCA5 on cell apoptosis in both breast cancer cell lines (p < 0.01)." (PMID 38978058, 2024). "Furthermore, the data of in vitro and in vivo revealed that depletion of FOXM1 alleviated the effect of CDCA5 overexpression on breast cancer." (PMID 38978058, 2024). "In addition, FOXM1 promotes EMT in breast cancer by directly binding the SLUG promoter and driving its expression." (PMID 39594778, 2024). "Overall, these findings establish that c-Src is a direct transcriptional target as well as an upstream activator of FOXM1, indicating that a positive feedback loop may reinforce the expression and activity of both proteins in some breast cancer subtypes." (PMID 36795481, 2023). "In summary, this study aimed to prepare a novel targeted delivery system using AuNPs as a carrier, AS1411 as a detector aptamer, ATP Apt (containing FOXM1 Apt complementary motif) to targeted co-delivery of FOXM1 Apt as a therapeutic molecule, and Dox to breast cancer cells." (PMID 37736517, 2023). "However, key effects of OGT have been observed in breast cancers including activation of the oncogenic transcription factors FoxM1 and a strong overexpression in breast cancer stem-like cells." (PMID 37231419, 2023). "To test whether FOXM1 plays a role in MAD2 tolerance in human cell, we infected MAD2-expressing human breast cancer cell lines with either an empty vector (EV) or with doxycycline-inducible human FOXM1 lentiviral vector (expressing FOXM1b or FOXM1c isoforms)." (PMID 37452072, 2023). "Targeting FOXM1 blocks proliferation and progression in models of luminal B–like breast cancer." (PMID 36795481, 2023). "That FOXM1 is an aggressiveness factor in human breast cancers is increasingly well established." (PMID 37370117, 2023). "Also, the AuNPs-AFPA group had reduced tumor growth rate compared with the AuNPs-AFPA-Dox group due to the lack of Dox, displaying the importance of combination therapy (co-delivery of Dox and FOXM1 Apt) in the treatment of breast cancer." (PMID 37736517, 2023). "In pre-symptomatic types of breast cancer, FOXM1 is necessary for augmentation and mitosis and modulates the genes transcription factors, such as p27kip1, cyclin D1, and cdc25, that are affiliated with cell division modulation at the G1-S and G2-M transition points." (PMID 37626655, 2023).